DEPDC5 (DEP domain containing 5, GATOR1 subcomplex subunit)
Description:
As a component of the GATOR1 complex functions as an inhibitor of the amino acid-sensing branch of the mTORC1 pathway. In response to amino acid depletion, the GATOR1 complex has GTPase activating protein (GAP) activity and strongly increases GTP hydrolysis by RagA/RRAGA (or RagB/RRAGB) within heterodimeric Rag complexes, thereby turning them into their inactive GDP-bound form, releasing mTORC1 from lysosomal surface and inhibiting mTORC1 signaling. In the presence of abundant amino acids, the GATOR1 complex is negatively regulated by GATOR2, the other GATOR subcomplex, in this amino acid-sensing branch of the TORC1 pathway. Within the GATOR1 complex, DEPDC5 mediates direct interaction with the nucleotide-binding pocket of small GTPases Rag (RagA/RRAGA, RagB/RRAGB, RagC/RRAGC and/or RagD/RRAGD) and coordinates their nucleotide loading states by promoting RagA/RRAGA or RagB/RRAGB into their GDP-binding state and RagC/RRAGC or RagD/RRAGD into their GTP-binding state. However, it does not execute the GAP activity, which is mediated by NPRL2.
Synonyms: KIAA0645; DEP.5; DEE111; FFEVF; FFEVF1; FPEVF
Tractability: Small molecule: a structure with a bound ligand is known. PROTAC: UniProt records ubiquitination sites on it; ubiquitination databases record sites on it; its protein half-life has been measured.
Gene: Protein-coding gene on chromosome 22 (31,753,867 to 31,908,033, forward strand). Ensembl gene ENSG00000100150.
Subcellular location: Lysosome membrane; Cytoplasm, cytosol; Cytoplasm, perinuclear region
Pathways (Reactome):
Cellular responses to stimuli: Amino acids regulate mTORC1
Gene Ontology:
Molecular function: protein-containing complex binding; small GTPase binding; GTPase activator activity
Biological process: cellular response to amino acid starvation; negative regulation of TORC1 signaling; positive regulation of autophagy; intracellular signal transduction
Cellular component: Cul3-RING ubiquitin ligase complex; GATOR1 complex; lysosomal membrane; lysosome; cytosol; perinuclear region of cytoplasm; cytoplasm
Genetic constraint (gnomAD): Loss-of-function variants: 66 observed, 200.89 expected, observed/expected ratio (o/e) 0.33, 90% interval 0.27 to 0.4. The upper end of that interval is the gene's LOEUF score, 0.4, which puts it in group 1 of 6, group 1 being the genes least tolerant of losing a copy. Missense variants: 1,639 observed, 2,109.8 expected, observed/expected ratio (o/e) 0.78, 90% interval 0.75 to 0.81. Synonymous variants: 720 observed, 777.83 expected, observed/expected ratio (o/e) 0.93, 90% interval 0.87 to 0.98.
Gene-disease validity (ClinGen):
ClinGen rates the evidence that DEPDC5 causes each of these diseases.
focal epilepsy (autosomal dominant): Definitive. A seizure caused by a localized disorder.
Homologues: Orthologues: macaque YWHAH (99% identical), chimpanzee DEPDC5 (99% identical), dog DEPDC5 (96% identical), rabbit DEPDC5 (95% identical), pig DEPDC5 (95% identical), rat Depdc5 (95% identical), guinea pig DEPDC5 (94% identical), mouse Depdc5 (94% identical), tropical clawed frog depdc5 (80% identical), zebrafish depdc5 (74% identical), Drosophila melanogaster Iml1 (37% identical), Caenorhabditis elegans T08A11.1 (26% identical).
Diseases named in the same sentence as DEPDC5 in open-access papers:
DEPDC5 is named in the same sentence as 100 diseases in open-access papers, as found by Europe PMC text mining. Sharing a sentence is not in itself a finding about the gene and the disease. The quoted sentences say what the papers report.
epilepsy (71 papers, 2014 to 2026). A brain disorder characterized by episodes of abnormally increased neuronal discharge resulting in transient episodes of sensory or motor neurological dysfunction, or psychic dysfunction. "Abnormal brain structure is a significant feature of epilepsy phenotypes associated with DEPDC5 gene variants." (PMID 41141423, 2025). "Studies have shown incomplete penetrance and phenotypic heterogeneity associated with DEPDC5-related epilepsies." (PMID 40546503, 2025). "Future studies with glia- and neuron-specific promoters are needed to fully characterize the cell-autonomous and non-cell-autonomous mechanisms underlying the neuroinflammation and epilepsy phenotype identified in Depdc5-knockout models." (PMID 40996830, 2025). "In our case, the presence of a known pathogenic DEPDC5 variant in the child and a history of epilepsy in three generations on the maternal side strongly suggest a familial epilepsy syndrome." (PMID 40546503, 2025). "All existing Depdc5-related epilepsy mouse models result in loss of DEPDC5 before or during neurogenesis." (PMID 40996830, 2025). "DEPDC5 mutation-related epilepsy is characterized by overactivity of the mammalian target of rapamycin complex 1 (mTORC1) signaling pathway and is primarily focal epilepsy." (PMID 40546503, 2025). "Mutations of the DEP Domain Containing 5 gene (DEPDC5), a mechanistic Target of Rapamycin (mTOR) inhibitor involved in amino acid sensing, are associated with neurological diseases such as epilepsy and/or autism spectrum disorder (ASD)." (PMID 40704780, 2025). "The current study is the first to our knowledge to demonstrate that postnatal loss of DEPDC5 and subsequent hyperactivation of mTORC1 signaling is sufficient to recapitulate the DEPDC5-related epilepsy phenotypes of FCD II pathology and seizures." (PMID 40996830, 2025). "DEPDC5 variants account for most GATOR1-related epilepsies (83%), possibly due to the greater length of the DEPDC5 transcript." (PMID 40426219, 2025). "In this study, we describe the clinical phenotypes and genetic characteristics of eight children with DEPDC5 gene variant-associated epilepsy, including the identification of four de novo mutations." (PMID 41141423, 2025). "The aim is to expand understanding of the phenotypic diversity associated with DEPDC5 gene variants and their impact on epilepsy." (PMID 41141423, 2025). "Exome sequencing identifies rare variants in epilepsy-associated genes (e.g., DEPDC5, CHD2) enriched in DS patients, with SCN1A-DEPDC5 co-mutations often associated with focal cortical dysplasia." (PMID 40772259, 2025). "Loss of DEPDC5 gene function after early brain development can still lead to epilepsy in mice providing critical insight into the developmental windows that lead to epilepsy and implications for genetic rescue." (PMID 40996830, 2025). "Studies have indicated that the majority of patients with DEPDC5 gene variant-associated epilepsy exhibit drug-refractory epilepsy." (PMID 41141423, 2025). "This case report discusses a young male child with a pathogenic variant of DEPDC5, who has a positive family history of seizure disorders." (PMID 40546503, 2025). "Familial focal epilepsy was the first epilepsy phenotype identified to be associated with DEPDC5 gene variants, and it has been widely reported in international studies." (PMID 41141423, 2025). "In this study, we showed that epilepsy patients with loss of function DEPDC5 mutations had reduced peripheral CD8+ T cells whereas high DEPDC5 expression positively correlated with tumor infiltration of CD8+ T cells as well as overall cancer patient survival." (PMID 38763950, 2024). "Another example involves DEPDC5-related epilepsy, in which frameshift mutations in DEPDC5 result in improper complex formation with the GATOR1 complex, a negative regulator of mTORC1." (PMID 38463392, 2024).
epilepsy (continued). "Haploinsufficiency is the likely mechanism underlying the pathogenesis of DEPDC5 mutations, and epilepsy related to DEPDC5 variants is inherited in an autosomal dominant manner." (PMID 38974383, 2024). "DEPDC5, a known epilepsy risk gene encoding DEP domain-containing protein (DEPDC) 513–15, is an essential component of the GATOR1 that also contains NPRL2 and NPRL310." (PMID 38763950, 2024). "This gene is well-established in familial focal epilepsy with variable foci, and while no family members were clinically affected in this case, the finding aligns with the known reduced penetrance observed in DEPDC5-associated epilepsies." (PMID 39767570, 2024). "DEPDC5 has also been studied in the context of epilepsy since loss-of-function mutations in this gene have been implicated in multiple types of neuronal dysfunction." (PMID 38763950, 2024). "Pleckstrin domain-containing protein 5 (DEPDC5) has been implicated in focal epilepsy, brain malformation, and sudden unexplained death in epilepsy." (PMID 36733671, 2023). "DEPDC5 mutations account for 83% of all GATOR1-related epilepsies, while the remaining 17% is made up of NPRL2 (6%) and NPLR3 (11%) variants." (PMID 34632383, 2021). "Nearly 85% of GATOR1 mutations in epilepsies account for changes in DEPDC5 with both somatic and germline mutations detected all through the gene without clustering." (PMID 34685669, 2021). "Analysis on epilepsy-related DEPDC5 variants revealed that malformations of cortical development (MCDs) had a tendency of higher frequency of null mutations than those without MCD." (PMID 32848577, 2020). "On the other hand, nonsense mutations in other epilepsy genes (e.g., DEPDC5) have also been detected in control individuals, and pLI scores should be interpreted with caution." (PMID 32038177, 2020). "Together, these data support mTORC1 hyperactivation as the likely pathogenic mechanism that underpins DEPDC5 loss of function in humans and highlights the potential utility of mTORC1 inhibitors in the treatment of DEPDC5-associated epilepsy." (PMID 28974734, 2017). "The DEPDC5 gene mutation has been identified in both familial and sporadic cases of epilepsy." (PMID 40546503, 2025). "DEPDC5-associated epilepsy has an autosomal dominant inheritance." (PMID 40546503, 2025). "More recent studies, utilising broader genetic testing strategies, suggest that EAF may be more genetically heterogeneous, with causal variants in other epilepsy-associated genes also described, including DEPDC5 and SCN1A." (PMID 40381056, 2025). "In recent years, pathogenic variants in the DEPDC5 gene have been linked to a broad spectrum of epilepsy phenotypes, ranging from mild conditions such as febrile seizures and febrile seizure plus to severe developmental epileptic encephalopathies like West syndrome." (PMID 41141423, 2025). "Most patients with DEPDC5 mutations have a normal brain MRI; however, some may exhibit epilepsy associated with cortical malformations or neuropsychiatric disorders such as developmental delay/ID and ASD." (PMID 39767570, 2024). "Frequently associated focal cortical dysplasia, the broad spectrum of DEPDC5-related epilepsies appears ever more relevant to the hypothesis of a ‘two-hit’ germline and somatic mutational mechanism." (PMID 36639812, 2023). "Two individuals with DEPDC5 germline variants also had a positive family history of epilepsy." (PMID 37946310, 2023). "GATOR1-related epilepsies caused by DEPDC5, NPRL2, and NPRL3 variations exhibit various phenotypes consisting of sleep-related focal hypermotor seizures, infantile spasms, and other focal epilepsies, including frontal, temporal, occipital, parietal, centrotemporal epilepsies." (PMID 34376795, 2022).
epilepsy (continued). "Similarly, human neural progenitor cells (NPCs) with heterozygous LOF DEPDC5 mutation from epilepsy patients iPSCs displayed elevated mTOR signaling reflected by S6 phosphorylation and larger soma size, which were reversed by rapamycin treatment." (PMID 35359577, 2022). "In particular, observation of an excellent response to the KD among patients with epilepsy caused by the DEPDC5 mutation may be important." (PMID 35160058, 2022). "Thus, DEPDC5 mutations are more frequent in epilepsies in comparison with mutations in other GATOR1 members." (PMID 34685669, 2021). "The more recent discovery of epilepsy-causative NPRL2 and NPRL3 variants and the greater length of the DEPDC5 transcript (5551 bp) compared with NPRL2 (1700 bp) and NPRL3 (2881 bp) have been offered as explanations for the increased frequency of DEPDC5-associated epilepsies." (PMID 34632383, 2021). "For example, an individual may have epilepsy due to an inherited stop‐gain variant in the gene DEPDC5, but may also have an HLA allele that independently increases the risk for a severe cutaneous adverse reaction to carbamazepine." (PMID 34288049, 2021). "All previously reported epilepsy-related DEPDC5 variants were reviewed." (PMID 32848577, 2020). "DEPDC5 mutations have recently been shown to cause epilepsy in humans." (PMID 28974734, 2017). "However, it remains unknown whether and how DEPDC5 mutation impacts firing and wiring that account for the pathologic defects in epilepsy." (PMID 35359577, 2022). "Similarly, the higher recurrence of NPRL2 mutations in cancers and DEPDC5 mutations in epilepsies could be related with the specific moonlighting functions of these GATOR1 members beyond the regulation of the mTORC1 pathway." (PMID 34685669, 2021). "Furthermore, mutations in other genes in the PI3K/Akt/mTOR pathway, including AKT3, PIK3CA, and DEPDC5, may also cause epilepsy." (PMID 34040629, 2021). "In vitro functional studies indicate that DEPDC5 is an inhibitor of mTORC1 signalling, suggesting that DEPDC5-associated epilepsy may result from aberrant mTORC1 signalling, as is the case in tuberous sclerosis patients who often have epilepsy." (PMID 28974734, 2017). "The treatment of DEPDC5-related epilepsies is based on their phenotype and genotype characteristics, with conventional anti-seizure medications (ASMs) being the initial approach." (PMID 40546503, 2025). "Disruption of mTOR signaling due to variants in its repressors such as TSC1, TSC2, DEPDC5, PTEN or in its activators such as RHEB, and MTOR lead to a set of disorders characterized by early onset and often drug-resistant epilepsies called mTORopathies." (PMID 40792287, 2025). "This study reports the clinical and genotype characteristics of eight children with DEPDC5-related epilepsy diagnosed in the Department of Neurology at Hebei Children’s Hospital between April 2020 and November 2024." (PMID 41141423, 2025). "All prior animal models of Depdc5-related epilepsy knocked out Depdc5 either before or during neurogenesis and demonstrated aberrant neuronal migration in addition to sustained postnatal dysfunction in mTORC1 signaling." (PMID 40996830, 2025). "We therefore performed longitudinal, week-long video electroencephalography (EEG) recordings in 3 focal Depdc5-knockout mice to evaluate the incidence of epilepsy." (PMID 40996830, 2025). "While most individuals with DEPDC5-related epilepsy maintain normal cognitive function, there have been cases where intellectual disability, autism spectrum disorder, or other psychiatric conditions are present." (PMID 40546503, 2025). "Our preclinical mouse model can support testing of gene-based therapies for patients with DEPDC5-related epilepsy and FCD." (PMID 40996830, 2025). "DEPDC5 and NPRL3 were two of the most common monogenic causes of epilepsy across 14 NGS studies in adults with epilepsy, together accounting for 7% of all genetic diagnoses made." (PMID 40381056, 2025).
epilepsy (continued). "The likely reason for the underreporting of lesions in DEPDC5-related epilepsy is that the lesions are small - either at the cellular or tissue level - making them difficult to detect." (PMID 40546503, 2025). "Our findings confirm that variants in mTOR pathway genes (not only in DEPDC5) are present in patients with ICA and underline the potential risk of sudden unexpected death in epilepsy." (PMID 40971258, 2025). "Mechanistically, the DEPDC5 gene contributes to epilepsy development by regulating the mTOR pathway." (PMID 41141423, 2025). "We identified several CNVs involving known epilepsy genes, with four families harboring intragenic deletions or duplications disrupting the DEPDC5 gene." (PMID 38101940, 2024). "A study of 16 patients with DEPDEC5 mutation-related epilepsy and SUDEP included 4 patients who presented with SHE, with four detected DEPDC5 mutations in these patients." (PMID 38966089, 2024). "The Depdc5 gene deletion in the mouse forebrain dorsal progenitors causes PNN loss, resulting in PV+ interneuron degeneration and the onset of epilepsy." (PMID 38673819, 2024). "Although the average age of onset for DEPDC5-related epilepsy is during the preschool years, seizures in this study began at 15 years old." (PMID 39767570, 2024). "We also identified CNVs affecting monogenic epilepsy genes, including four families with CNVs disrupting the DEPDC5 gene, and a de novo deletion of HNRNPU in one affected individual from a multiplex family." (PMID 38101940, 2024). "Three genes remained significant when we combined all epilepsy subtypes: DEPDC5 (log[OR]=2.1, P=3.4×10−15), NEXMIF (log[OR]=4.1, P=6.3×10−9), and SCN1A (log[OR]=2.7, P=3.5×10−8)." (PMID 36865150, 2024). "The variation was verified to impact the alternative splicing of DEPDC5 and introduce an early stop codon that resulted in the pre-maturation and loss of function of DEPDC5, which, as a consequence, might disturb the mTOR signaling pathway and lead to epilepsy." (PMID 38974383, 2024). "Asymptomatic heterozygotes are common in DEPDC5-related epilepsy families, leading to reduced penetrance of approximately 60%." (PMID 39767570, 2024). "NPRL3‐related epilepsy is slightly more common among females and a similar gender disparity was reported in the prevalence of DEPDC5 and NPRL2‐related epilepsy." (PMID 37491868, 2023). "Malformations of cortical developments are common in NPRL3 patients, especially FCD 2a, and their prevalence is comparable to DEPDC5‐related epilepsy." (PMID 37491868, 2023). "Studies of families affected by DEPDC5-mediated epilepsy have contributed significantly to our current understanding of FCD." (PMID 35163267, 2022). "Rapamycin reduced seizures in rodent models of DEPDC5-related epilepsy and focal cortical dysplasia type II." (PMID 34632383, 2021). "Among variants transmitted from heterozygous carrier parents within cardiac or seizure disorder genes, two variants associated with autosomal dominant conditions were classified as contributory to death in two cases (SCN1A and DEPDC5)." (PMID 34930847, 2021). "We further reviewed the correlation of genotype and phenotype in all previous literature regarding DEPDC5-related epilepsy." (PMID 34239491, 2021). "Incomplete penetrance is a prominent feature of DEPDC5-related epilepsy, with the rate of penetrance ranging from 25 to 100%." (PMID 34239491, 2021). "In preclinical models of GATOR1-related epilepsies, Depdc5 conditional knockout mice display a propensity for terminal seizures, resembling the human phenomenon of SUDEP." (PMID 34632383, 2021). "Previous studies have showed that DEPDC5 mutations are associated with diverse focal epileptic phenotypes, ranging from mild rolandic epilepsy to severe MCD-associated epilepsies." (PMID 32848577, 2020). "The present study suggests that the phenotypical spectrum of DEPDC5 variants potentially includes FEFS + /FS, which warrants validation on a large cohort of FS-related epilepsies." (PMID 32848577, 2020).